ALB (albumin)
Diseases named in the same sentence as ALB in open-access papers (continued):
Sharing a sentence is not in itself a finding about the gene and the disease.
type 2 diabetes (continued). "Although the findings of prior studies have confirmed the effectiveness of auricular acupressure in improving Type 2 diabetes in older adults, few studies have investigated the use of glycated hemoglobin, albumin, and fructosamine in glycemic control due to testing cost and inconvenience." (PMID 40586734, 2025). "Conversely, high albumin concentrations may protect against early glycemic deterioration and type 2 diabetes progression." (PMID 39339668, 2024). "A recent study combining the NHANES and Mendelian randomization study showed a significant positive association between serum calcium and type 2 diabetes, albeit without adjusting for serum albumin." (PMID 38505748, 2024). "In a preceding cross-sectional association on type II diabetes, participants experiencing nocturia exhibited markedly lower serum albumin levels than their counterparts without nocturia." (PMID 39146317, 2024). "American Diabetes Association (ADA)recommends yearly evaluation of all patients with type 2 diabetes for renalfunction (eGFR) and urinary albumin levels, with use of SGLT2i, RAASi (ACEi, ARB,ARNI) and MRA as tolerated by patients, using a patient tailored approach." (PMID 39076544, 2024). "Statistics from the US National Health and Nutrition Examination Survey up to 2012 revealed evidence of CKD based on eGFR and/or urinary albumin/creatinine ratio in roughly 40% of individuals with type 2 diabetes and approximately 60% of people aged 65 or older with type 2 diabetes." (PMID 39125705, 2024). "The same group tested the effects of spironolactone in 20 diabetic kidney disease patients (both type 1 and type 2 diabetes) with nephrotic range proteinuria and reported that the mean urinary albumin levels were reduced by 32% by spironolactone after 2 months." (PMID 37175424, 2023). "Our research points out that in the future, we might pay attention to serum albumin levels at the same time, especially in patients with type 2 diabetes who undergo PCI." (PMID 36747210, 2023). "However, albumin was found to increase platelet adhesion to collagen and fibrinogen in patients with type 2 diabetes." (PMID 37682850, 2023). "In type 2 diabetes patients, the level of ALB is positively correlated to renal function." (PMID 37576498, 2023). "However, in patients with type 2 diabetes and healthy controls, the urinary 8-OHdG level was inferior to the urinary albumin excretion when predicting the development of DKD." (PMID 37109492, 2023). "It was also found that HOMA-IR was significantly associated with urinary albumin in male patients with type 2 diabetes, but not in female patients." (PMID 36072812, 2022). "The primary objective of this study was to evaluate whether there was a relationship between serum albumin and DR among people with type 2 diabetes." (PMID 35709212, 2022). "Characteristics of patients with Type 2 diabetes grouped by Urine albumin and creatinine values." (PMID 36550864, 2022). "Finally, we note C4b‐binding protein was elevated in albumin knockout mice compared with WT, and this protein has been shown to be protective against type 2 diabetes." (PMID 35238481, 2022). "Altered mean platelet volume (MPV) and plasma albumin has been reported in type 2 diabetes (T2D)." (PMID 34078390, 2021). "This study aimed to evaluate the correlation of urinary liver-type fatty acid-binding protein (L-FABP) levels with renal function and to compare the role of urinary albumin-to-creatinine ratio (ACR) with urinary L-FABP in early detection of DN in type 2 diabetic patients." (PMID 33033456, 2020). "In this model, fasting glucose, platelet counts, waist circumference, age, gamma-glutamyl-transferase (GGT), prothrombin time and aspartate aminotransferase (AST), followed by INR, albumin and type 2 diabetes were predictors of advanced fibrosis, identified by Random Forest feature elimination." (PMID 32523101, 2020).
type 2 diabetes (continued). "Furthermore, the current study was unique in its ability to consider several blood biomarkers commonly measured in usual clinical practice among type 2 diabetics, and blood urea nitrogen, albumin, and hemoglobin A1c were among the final predictors." (PMID 31837035, 2020). "The type 2 diabetic rats in our study could be determined to have early DN due to the important characteristic of a significant increase in urinary albumin excretion." (PMID 33097050, 2020). "Therefore, it has been recommended that patients with type 2 diabetes and increased urinary albumin excretion should be check for increased left ventricular mass as an important and potentially reversible cardiovascular risk factor." (PMID 31237136, 2019). "In another study, esaxerenone treatment was associated with a reduction in the urine albumin-to-creatinine ratio (UACR) in patients with type 2 diabetes and albuminuria (NCT02345057, unpublished data)." (PMID 31239535, 2019). "Those patients with severe CaC (CaCs ≥400 HU) were older, had a longer haemodialysis vintage, showed higher prevalence of type 2 diabetes, previous cardiologic events, and exhibited higher triglyceride serum concentration and lower serum albumin levels than mild-moderate CaC subjects (CaCs< 400 HU)." (PMID 31138150, 2019). "Previous studies have shown that administering 2 weeks of CSII to newly diagnosed patients with type 2 diabetes resulted in almost a 1% decrease in HbA1c and an 8% decrease in glycated albumin, while the time taken to achieve glycemic targets was around 3 to 5 days." (PMID 30420969, 2018). "Furthermore, mannan-binding lectin positively correlates with urinary albumin excretion in patients with type 1 diabetes as well as type 2 diabetes." (PMID 29910771, 2018). "Generation of neo-epitopes on albumin might be involved in the induction of autoantibodies in type 2 diabetes." (PMID 28192530, 2017). "The development of microalbuminuria in type 2 diabetes defined as a urinary albumin excretion rate (UAER) of ≥20 μg/min strongly predicts end stage renal disease and is also an independent risk factor for the development of cardiovascular disease, as well as cardiovascular mortality." (PMID 26824045, 2016). "Thus, we performed 24-hour ambulatory blood pressure monitoring in a prospective study of normotensive adults with type 2 diabetes and normal urinary albumin excretion at the time of enrollment." (PMID 26824045, 2016). "The present study assessed for the first time whether long-term low-dose aspirin affects the incidence of positive urine dipstick albumin in patients with type 2 diabetes." (PMID 26808136, 2016). "In the JPAD2 cohort study, we analyzed whether long-term low-dose aspirin therapy affects eGFR and the incidence of positive urine dipstick albumin in patients with type 2 diabetes." (PMID 26808136, 2016). "Our study provides relevant information on levels of serum 25(OH)VD3, HIF-1α, VEGF, vWf, and IGF-1 in a large-scale cohort to further understand the law of their changes and to clarify their correlation in type 2 diabetes patients with different urine albumin creatinine ratio." (PMID 27069929, 2016). "Urinary albumin excretion is associated with high IOP in the type 2 diabetes population without renal insufficiency." (PMID 24788677, 2014). "In summary, this study demonstrated that urinary albumin excretion is associated with high IOP in type 2 diabetes patients without renal insufficiency." (PMID 24788677, 2014). "In this respect, a previous study showed that 8 week treatment with sulodexide, a mixture of the glycocalyx components heparan and chondroitin sulfates, improved both sublingual glycocalyx dimensions as well as the vascular retention of albumin in type II diabetes patients." (PMID 23383178, 2013).
type 2 diabetes (continued). "However, Giordano has also shown that a low-protein diet is effective in reducing whole-body proteolysis and is associated with a decrease in protein oxidation and an increase in serum albumin levels in type 2 diabetic patients." (PMID 24303049, 2013). "Thus, in patients with type 1 diabetes, treatment with unfractionated heparin, sulodexide or LMWH decreased the albumin excretion rate, whereas in type 2 diabetes, the effect on albuminuria seems less consistent." (PMID 22400116, 2012). "In addition, Zinc supplementation alone also reduced albumin excretion in microalbuminuric patients with type-2 diabetes." (PMID 22515411, 2012). "Similarly micronutrient supplementation including vitamins C and E together with Magnesium and Zinc significantly lowered urinary albumin excretion (a marker for glomerular dysfunction) in patients with type-2 diabetes." (PMID 22515411, 2012). "Further, plasma OPG was associated with PAD in our type 2 diabetes patients in univariate logistic regression analysis, but not after adjusting for age, HbA1c and U-albumin creatinine ratio." (PMID 21838881, 2011). "In contrast, a recent investigation of 421 Asian Indian type 2 diabetics did find an association between the AGT 235 T-allele and renal insufficiency (defined as plasma creatinine ≥ 3 mg/dl and/or urinary albumin excretion rate > 200 mcg/min) (OR 2.68, 95%CI 2.01 to 3.57)." (PMID 19327134, 2009). "The logistic regression model incorporating with glycated albumin, hs-CRP and other major risk factors of atherosclerosis may be useful for screening CAD in patients with type 2 diabetes." (PMID 17178005, 2006). "Rat models of type 2 diabetes were successfully established via the administration of streptozotocin and a high-fat diet, as evidenced by increased blood glucose levels, kidney weight to body weight (KW/BW) ratio, serum albumin, creatinine, and urea levels, kidney damage, and oxidative stress." (PMID 40362229, 2025). "When MARS was first introduced to treat patients with hepatic failure and coma, it was believed that its effective removal of protein-bound toxins of liver failure was due to albumin, which somehow entered the membrane to directly contact plasma proteins and transfer toxins to the albumin." (PMID 37384883, 2023). "Another study showed that serum albumin, serum creatinine, albumin/creatinine ratio, and hemoglobin are multivariate risk factors for ESRD, which were taken from 1513 subjects included in the reduction of endpoints in noninsulin-dependent diabetes with the Angiotensin II Antagonist Losartan study." (PMID 37371759, 2023). "Similarly, higher GO intake was associated with lower urinary albumin excretion in individuals with type 2 diabetes only (normal glucose metabolism STD β: 0.04; 95% CI: −0.03, 0.10; prediabetes: −0.07; −0.21, 0.08; and type 2 diabetes: −0.13; −0.26, −0.01, respectively." (PMID 36055771, 2022). "Moreover, other studies performed among type 2 diabetic patients suggested that overall antioxidants supplementation significantly decreased the levels of urinary albumin excretion and oxidative stress, thereby improving glomerular function and endothelial dysfunction." (PMID 35600816, 2022). "In particular, higher albumin level, metformin, insulin, and sulfonylureas were the independently protective factors, but older age and CCI score≥3 were the independent risk factors for all-cause death in patients with pulmonary TB and type 2 diabetes comorbidity." (PMID 34513785, 2021). "Therefore, a post hoc analysis was performed on two randomized controlled trials (n = 69), assessing effects of dapagliflozin 10 mg/day when added to renin–angiotensin system inhibition in patients with type 2 diabetes and urinary albumin-to-creatinine ratio ≥30 mg/g." (PMID 31159350, 2019).
type 2 diabetes (continued). "Similarly, Tseng has also reported lipid abnormalities in patients with type 2 diabetes with regards to different stages of albuminuria and suggested a close link between uric acid and increased urinary albumin excretion rate in type 2 diabetic patients of Taiwan." (PMID 24918095, 2014). "Also, the previous study results showed that endothelial dysfunction assessed by brachial artery flow-mediated dilation (FMD) was associated with urinary albumin excretion (UAE) and was interrelated with carotid IMT in type 2 diabetic patients with microalbuminuria." (PMID 23573090, 2013). "It was conducted in type 2 diabetes patients > 30 years of age, with an eGFR of 30-<90 ml per minute per 1.73 m2 (CKD), a urinary albumin to creatinine ratio of >300–5,000 mg/g (macroalbuminuria), and already treated with renin-angiotensin system blockade." (PMID 39950157, 2025). "A reduction in urinary albumin–creatinine ratio from baseline to month 4 was associated with a lower risk of the primary and kidney composite end points with a similar risk gradient for participants with and without type 2 diabetes (P-interaction: 0.10 and 0.19, respectively)." (PMID 39475817, 2024). "We used data from the RADAR and SONAR trials that recruited participants with type 2 diabetes and CKD [eGFR 25–75 mL/min/1.73 m2, urine albumin-to-creatinine ratio of 300–5000 mg/g]." (PMID 37716952, 2023). "High TSH and FT4 (or T4), lower FT3 (or T3), and thyroglobulin antibodies (TgAb) positivity correlated with higher urine albumin-to-creatinine ratio (UACR) and lower eGFR levels in type 2 diabetes patients." (PMID 37809188, 2023). "Compared to the CON group, mice with type 2 diabetes showed a significant increase in serum levels of ALT and AST, while TP and ALB levels exhibited a significant decrease." (PMID 37509732, 2023). "The literature to date describes that in patients with type 2 diabetes, both VASH-1 and UACR (Urine Albumin-to-Creatinine Ratio) are positively correlated with the concentration of glycated hemoglobin (HbA1C)." (PMID 35372578, 2022). "In isolated type 2 diabetic mice hearts, metabolic effects of 35 min EMPA (1 μM) perfusion in the presence of albumin on 13C-glucose or 13C-palmitate metabolism have been examined." (PMID 35303888, 2022). "Univariate analysis showed that risk factors for severe illness were obesity (BMI ≥ 28 kg/m2), presence of type 2 diabetes, lactate dehydrogenase (LDH) > 250 U/L, CRP > 10 mg/L, and ALB < 35 g/L." (PMID 32384078, 2020). "Asymptomatic elevations in urinary albumin excretion and serum creatinine levels, key measures of DKD, are frequently present in diabetic siblings of African American individuals with overt type 2 diabetes." (PMID 29854459, 2018). "Urinary albumin/creatinine ratio (ACR) was measured at baseline and after a median follow-up of 6.0 years in 161 patients with type 2 diabetes." (PMID 27975066, 2016). "In multivariate analyses, male gender, type 2 diabetes, a history of CVD, hemoglobin, albumin and GFR lost significance, while older age, the extent of proteinuria and higher CRP-levels remained significantly related to mortality (all p<0.05)." (PMID 25894587, 2015). "In this study including type 2 diabetic patients, urinary MCP-1 levels positively correlated with urinary excretion levels of albumin in all subjects." (PMID 26239462, 2015). "In our current study using a db/db mouse model of type 2 diabetes, we demonstrate that APF treatment has potential for use in the amelioration of glucose and lipid metabolism disorders, and can decrease urinary albumin excretion." (PMID 25803610, 2015). "In 16 patients with type 2 diabetes treated with 30 mg/day mitiglinide, levels of plasma glucose, FFA, and urinary albumin excretion were significantly decreased." (PMID 22748110, 2012).
type 2 diabetes (continued). "The purpose of this study was to evaluate the clinical value of serum glycated albumin and high-sensitivity C-reactive protein (hs-CRP) levels in predicting the presence of CAD in patients with type 2 diabetes." (PMID 17178005, 2006). "The aim of this study was to determine the clinical value of serum glycated albumin and high-sensitivity C-reactive protein (hs-CRP) levels for the prediction of CAD using logistic regression model in patients with type 2 diabetes." (PMID 17178005, 2006). "Serum glycated albumin and hs-CRP levels were significantly elevated in patients with type 2 diabetes and CAD." (PMID 17178005, 2006). "Although the normal physiologic ratio of FFA to albumin is approximately 2:1, serum FFA levels are greatly elevated in patients with obesity, type 2 diabetes, and proteinuric renal diseases, yielding ratios of 6:1 or higher." (PMID 15642122, 2005). "Recent findings highlight the clinical significance of low-level urine albumin excretion, e.g. uACR value > 10 mg/g significantly predicts CKD progression in type 2 diabetes, while a threshold of 16 mg/g in the general population is linked to higher cardiovascular mortality risk." (PMID 40835785, 2025). "In type 2 diabetes, increased serum galectin-9 correlates with declining GFR, while recombinant galectin-9 therapy in mouse models mitigates glomerular hypertrophy, albumin excretion, and TGF-β expression." (PMID 40904455, 2025). "They found that long-term low-dose aspirin does not affect eGFR or positive urine dipstick albumin in patients with type 2 diabetes." (PMID 39198874, 2024). "Similar results on albuminuria have been attained in a pooled analysis of randomized controlled trials evaluating the effect of dapagliflozin in patients with type 2 diabetes and stages 3b–4 CKD characterized by lower levels of albuminuria (urine albumin–creatinine ratio 40 mg/g)." (PMID 39502370, 2024). "Subgroup analyses suggest dapagliflozin is cost-effective irrespective of urinary albumin-to-creatine ratio and type 2 diabetes status." (PMID 38389710, 2024). "In this cross-sectional study, we analyzed data from 1947 type 2 diabetic patients and found a significant negative correlation between serum albumin (ALB) levels and diabetic retinopathy (DR)." (PMID 38369636, 2024). "We used db/db mice as a type 2 diabetic mice model and db/m mice as a non-diabetic control to observe the correlations between the lncRNA Dlx6-os1 expression level, urinary albumin protein level, and the degree of podocyte injury." (PMID 36854759, 2023). "Our research aimed to design and perform computational analysis of the fusion proteins with high affinity and specificity for human serum albumin and a protease-resistant GLP-1 peptide to produce potent GLP-1 agonists with an extended plasma half-life for the treatment of type 2 diabetes." (PMID 37853095, 2023). "Furthermore, studies have pointed out that observing changes in the urinary albumin-to-creatinine ratio (UACR) can predict changes in clinical outcomes and mortality risks for type 2 diabetes patients." (PMID 37964953, 2023). "Patients with type 2 diabetes and CKD (urinary albumin-to-creatinine ratio [UACR] of ≥30 to <300 mg/g and estimated glomerular filtration rate [eGFR] of ≥25-≤90 mL/min/1.73 m2, or UACR of ≥300 to ≤5,000 and eGFR of ≥25 mL/min/1.73 m2) on optimized renin–angiotensin system blockade." (PMID 37745646, 2023). "In the RIACE trial, 15,773 individuals with type 2 diabetes were enrolled and classified based on albuminuria and eGFR in four groups: no DKD (Alb−/eGFR−), albuminuria alone (Alb+/eGFR−), reduced eGFR alone (Alb−/eGFR+), or both albuminuria and reduced eGFR (Alb+/eGFR+)." (PMID 37238622, 2023). "We found diastolic BP (importance 2.1), albumin–creatinine ratio (importance 1.6), and gender (importance 1) to be the significant predictors for screening CAN, which is the most common complication among Bangladeshi patients with type 2 diabetes." (PMID 35207179, 2022).